TREM1 (triggering receptor expressed on myeloid cells 1)
Diseases named in the same sentence as TREM1 in open-access papers (continued):
Sharing a sentence is not in itself a finding about the gene and the disease.
atherosclerosis (continued). "Several studies have highlighted the implication of TREM-1 activation in various pathophysiologic processes that contribute to atherosclerosis and its complications such as endothelial dysfunction, inflammatory lipid accumulation, plaque destabilization and increased thrombogenicity." (PMID 36944850, 2023). "However, investigation and characterization of the pathways and targeting TREM-1 to exert its protective effects in atherosclerosis must be done to solidify its potential as a target of clinical significance." (PMID 36856919, 2023). "This study provides molecular and biochemical evidence that inhibiting of TREM-1 may be a novel strategy and a promising target for the treatment of atherosclerosis." (PMID 35637975, 2022). "In both heavy smokers and patients with CAD the increase in TREM1 and CCL11 was also found, indicating that an increase in these proteins may be potential risk factors for atherosclerosis development." (PMID 36189218, 2022). "Our results uncover a new link between ox-LDL and TREM-1 and may provide insight into this interaction in the context of atherosclerosis." (PMID 35637975, 2022). "These cytokines comprise the inflammatory effectors of TREM-1 responsible for the pathological effects of TREM-1 signaling described in septic shock, rheumatoid arthritis, atherosclerosis, myocardial infarction, inflammatory bowel disease and retinal neovascular disorders." (PMID 34956864, 2021). "TREM1 has been characterized as a major player in the pathophysiology of acute inflammatory diseases of different etiologies such as acute myocardial infarction, atherosclerosis, and infectious diseases." (PMID 33525982, 2021). "It has been reported that TREM1 was involved in the pathogenesis of atherosclerosis." (PMID 34221733, 2021). "Genetic and pharmacological inhibition of TREM1 ameliorated atherosclerosis in mice." (PMID 31426806, 2019). "Recently, TREM-1 was shown to be a biomarker for atherosclerosis and ACS4, and evidence suggests that its inhibition using genetic or pharmacological methods may limit the development of experimental atherosclerosis." (PMID 30993014, 2019). "As TREM-1 is a key player in the pathogenesis of atherosclerosis, it is worth finding out how it could be used as a biomarker of atherosclerosis susceptibility with at-risk patients." (PMID 30205488, 2018). "Based on the distinct impact of TREM-1 on hypercholesterolemia-induced monopoiesis and its highly upregulated expression within aortic lesions, we propose TREM-1 as an attractive myeloid cell-specific target for attenuating the chronic inflammatory process in atherosclerosis." (PMID 27762264, 2016). "Here, we demonstrate that TREM-1 promotes cardiovascular disease by exacerbating atherosclerosis." (PMID 27762264, 2016). "In support of our hypothesis that TREM-1 may promote atherosclerotic lesion progression locally, we found highly upregulated expression of mRNA for TREM-1 also in human aortic tissue specimens displaying severe atherosclerosis." (PMID 27762264, 2016). "Besides, TREM-1-mediated pyroptosis was discovered in ox-LDL-treated endothelial cells (ECs) and could be the underlying reason of ECs dysfunction during atherosclerosis development." (PMID 38333413, 2024). "In addition, TREM1 promotes atherosclerosis by inducing monocytosis and foam cell formation." (PMID 35693550, 2022). "The role of TREM-1 in mounting a dysregulated and deleterious inflammation has been proven in acute diseases or syndromes such as septic shock, myocardial infarction, or stroke, but also in chronic disorders: inflammatory bowel diseases, atherosclerosis, arthritis, lupus, and cancer." (PMID 36699032, 2022). "Numerous researches have also indicated that TREM1 inhibitors could confer protective effect in pathological conditions with excessive immune responses, including stroke, myocardial infarction, inflammatory bowel diseases, atherosclerosis, fibrosis and cancer." (PMID 34721438, 2021).
atherosclerosis (continued). "While our findings show that TREM-1 can contribute to atherosclerosis through regulation of the BM and peripheral monocyte pool, resulting in increased monocyte/macrophage accumulation and lesion progression, our data also suggest that TREM-1 may promote atherosclerotic lesion progression in situ." (PMID 27762264, 2016). "The effects of TREM-1 and TLR-4 inhibition on early vessel thrombosis was under investigation because pro-inflammatory mediators TREM-1 and TLR-4 play a critical role in atheromatous plaque formation, atherosclerosis, and vessel stenosis." (PMID 35203642, 2022). "It has also been shown that TREM-1 apparently mediates ox-LDL-induced endothelial cell pyroptosis, a cell death process found in atherosclerosis, which is dependent on caspase-1 activation and IL-1β and IL-18 production." (PMID 33814983, 2021). "Our insinuation is based on how bacteria were found to play a part in pro-inflammatory reactions leading to atherosclerosis and the LPS component of the bacteria acting as DAMPS to activate TLRs, that are found to interact in synergy with TREM-1." (PMID 30205488, 2018). "It is remarkable how all of them approach cardiovascular diseases involving TREM-1 and the role it plays in inflammation either in acute settings like endocarditis and AMI, or in chronic conditions, such as in atherosclerosis." (PMID 30205488, 2018). "Overall, TREM-1 was found to be involved in the pathogenesis of acute and chronic cardiovascular conditions, such as acute myocardial infarction (AMI) and atherosclerosis." (PMID 30205488, 2018). "Moreover, to determine the translational impact of the TREM2/TREM1, and Olfr2 therapies, the development of induced pluripotent stem cells derived in-vitro vascular organoids may be beneficial to screen drugs that are more effective in lowering atherosclerosis disease burden in humans." (PMID 40384967, 2025). "Our investigations in an easy-to-make, low-maintenance and reproducible model, which is representative of the advanced stages of atherosclerosis in humans, showed that low ESS increased the expression of inflammatory molecules and matrix-degrading enzymes through the activation of TREM-1." (PMID 36944850, 2023). "Moreover, TREM-1 was found to be expressed in atherosclerotic human lesions, and inhibition of TREM-1 alleviated atherosclerosis in a murine model." (PMID 35637975, 2022). "The TREM-1-mediated proinflammatory effect has been identified in various infectious and noninfectious inflammatory conditions including atherosclerosis." (PMID 33814983, 2021). "Here the authors show that TREM-1 plays an important role in atherosclerosis, a chronic and non-infectious disease, by critically skewing myelopoiesis towards preferential monocyte differentiation and by contributing to CD36-driven cellular lipid accumulation." (PMID 27762264, 2016). "Blocking TREM-1 has been suggested to suppress inflammatory cytokine production and alleviate the progress of infectious and noninfectious diseases, including atherosclerosis." (PMID 35637975, 2022). "However, to date, the precise role of TREM-1 and its downstream factors orchestrating atherosclerosis inflammation has not been clarified." (PMID 35637975, 2022). "Fourth, even though adding LDL to the cultures would make them more relevant to human atherosclerosis, we elected not to add LDL in order to eliminate the confounding effect of LDL on TREM-1 and inflammation." (PMID 36944850, 2023).
colitis (37 papers, 2014 to 2025). Inflammation of the colon. "A study with TREM-1-deficient (Trem1−/−) mice and dextran-sulfate-sodium-induced colitis generated convincing results." (PMID 38191420, 2024). "TREM1 mRNA and protein upregulation was accompanied by an increased inflammatory response and disease severity in mouse models of colitis, which were attenuated in TREM1-deficient mice." (PMID 38370418, 2024). "Consistently, TREM1 deficiency compromises pro-inflammatory features of the monocyte-macrophage lineages, thus culminating in the inhibition of colitis in mice." (PMID 39095853, 2024). "Evidence has been emerging that colitis-associated monocytes upregulate the expression of TREM1, which is reckoned as a potent amplifier of pro-inflammatory responses." (PMID 39095853, 2024). "Consistently, a recent study that TREM-1 loss exacerbates colitis in several mouse models solidifies our results." (PMID 33767714, 2021). "On the other hand, colonic MP expression of TREM-1 is associated with colitis, and blocking TREM-1 abrogates local levels of monocyte chemoattractants and pro-inflammatory cytokines." (PMID 34650568, 2021). "In this study, we determined the effect of an anti-TREM-1 agonistic antibody (α-TREM-1) on colitis and identify its underlying mechanism of action." (PMID 33767714, 2021). "Previous studies using experimental mouse colitis models have shown that TREM-1 deficiency alleviates IBD by reducing the production of inflammatory mediators." (PMID 31189465, 2019). "A pathogenic role for TREM-1 in colitis was suggested by the finding that both soluble TREM-1 (sTREM-1) in serum and TREM-1 mRNA in inflamed colonic tissue were elevated in patients with IBD." (PMID 31189465, 2019). "In fact, in experimental sodium dextran sulfate-induced colitis, TREM-1 overexpression and pro-inflammatory activity are associated with ER stress and autophagy failure." (PMID 31546668, 2019). "To verify the importance of IL-22 in preventing the pathogenesis of DSS-induced colitis, we injected recombinant IL-22 into the peritoneal cavities of TREM-1-deficient mice every other day, starting 1 day prior to DSS administration." (PMID 31189465, 2019). "The potential of TREM-1 as a therapeutic target was already demonstrated for experimental colitis, influenza infection and LCL caused by L. major." (PMID 29670621, 2018). "Collectively, our findings indicate a disease-promoting role for TREM-1-expressing neutrophils in colitis-associated cancer." (PMID 29093489, 2017). "Intriguingly, although upon administration of 3% DSS Trem1−/− mice initially lost weight to a similar extent as Trem1+/+ mice, weight loss was considerably attenuated at 7 days post colitis induction and at 9 days Trem1−/− mice had already improved again." (PMID 24453980, 2014). "Inhibition of Trem-1 activity (either through genetic mutation or by the use of inhibitor peptides) restored normal functions and prevented inflammation in experimentally-induced colitis in mice." (PMID 36557633, 2022). "Moreover, TREM-1-deficient mice used in colitis and other experimental models of infection-driven inflammatory diseases exhibited no alterations in microbial clearance efficiency." (PMID 31581596, 2019). "To investigate whether the phenotype of TREM-1-mediated macrophages regulates IBD pathogenesis, we examined the effects of DSS-induced colitis on an in-house generated independent line of TREM-1-deficient (TREM-1 KO) mice." (PMID 31189465, 2019). "As support, in two murine models of dextran sodium sulfate-induced colitis, and colitis-associated azoxymethane-induced tumorigenesis, administration of the TREM-1 antagonist LP17 produces anti-inflammatory effects in the colon and decreases intestinal epithelial proliferation." (PMID 31546668, 2019). "Taken together, TREM-1 significantly contributed to colitis-associated tumor development." (PMID 29093489, 2017).
colitis (continued). "Furthermore, analogous to the CD4 T cell-induced colitis, TREM-1 deficiency resulted in reduced colonic mRNA expression of several pro-inflammatory mediators." (PMID 24453980, 2014). "Since neutrophil survival versus apoptosis could represent a deciding factor in the control of inflammation not only in the L. major infection model but also in the pathogenesis of experimental colitis, we compared the susceptibility of Trem1+/+ and Trem1−/− neutrophils to spontaneous apoptosis." (PMID 24453980, 2014). "In animal models of colitis, blocking or knocking out TREM-1 reduces inflammation and protects the intestinal barrier." (PMID 41226426, 2025). "In Leishmania major, influenza virus, and Legionella pneumophila infection models of colitis, Trem1−/− animals displayed reduced morbidity and immune-mediated pathology without impairing microbial clearance." (PMID 41226426, 2025). "Pharmacologic inhibition of TREM-1 with different therapeutic peptide, LR12, along with genetic knockdown of TREM-1, was also successful in protecting mice from severity of colitis." (PMID 38881893, 2024). "In this situation, almost all the studies have been carried out on in vivo mouse model of DSS-induced colitis leading to the conclusion that TREM-1 inhibition reduces colitis and tumor development within animal’s colon." (PMID 35875168, 2022). "We showed that TREM-1 is indispensable for the innate immune response and barrier function in colitis." (PMID 33767714, 2021). "TREM-1 activation using an α-TREM-1 antibody protects against colitis by rebalancing the microbiota and protecting the epithelium against the immune response as well as modulates the function of neutrophils and macrophages." (PMID 33767714, 2021). "This is the first study to demonstrate that stimulation of TREM-1 signaling using α-TREM-1 is effective at attenuating colitis." (PMID 33767714, 2021). "TREM-1 was reported to modulate autophagic activity and endoplasmic reticulum (ER) stress in colitis in mice." (PMID 33390769, 2021). "In contrast, in the mucosa of IBD patients and experimental models of colitis, TREM-1-expressing macrophage infiltration becomes markedly increased, amplifying intestinal inflammation and tissue damage through the secretion of pro-inflammatory mediators." (PMID 32456204, 2020). "TREM-1 pharmacologic blockade in vivo in mouse models of colitis confirmed the TREM-1 contribution to the exacerbation and perpetuation of chronic colon inflammation and its progression toward carcinoma development (see Section 7 for details)." (PMID 32456204, 2020). "Blocking of TREM1 in murine models of experimentally induced colitis ameliorated disease severity, suggesting TREM1 to be an attractive therapeutic target for IBD patients." (PMID 32987848, 2020). "In summary, our findings indicate that TREM-1 protects mice against acute DSS-induced colitis by promoting M1 macrophage polarization and IL-1β production, which contributes to IL-22 production by ILC3 that restores epithelial barrier integrity." (PMID 31189465, 2019). "Acute colitis was induced in C57BL/6 and TREM-1-deficient mice by the administration of dextran sodium sulfate (DSS)." (PMID 31189465, 2019). "Our findings indicate that TREM-1 protects mice against acute DSS-induced colitis by promoting ILC3 activation and the production of IL-22 that restores epithelial barrier integrity." (PMID 31189465, 2019). "Accordingly, the effects of TREM-1 inhibition, achieved by the administration of an antagonistic peptide to mice, were examined following the induction of DSS-induced colitis or colitis-associated carcinogenesis (CAC)." (PMID 31189465, 2019). "Inactivation of TREM-1, either by administering antagonist peptides or by engineering depletion, attenuates the severity of chemically induced experimental colitis." (PMID 31189465, 2019). "Here, we have generated an independent TREM-1 KO mouse line to unambiguously investigate TREM-1’s function during DSS-induced colitis." (PMID 31189465, 2019).
colitis (continued). "TREM-1 increases IL-1β production by M1 macrophages during DSS-induced colonic inflammation and thereby influences ILC3-mediated IL-22 production." (PMID 31189465, 2019). "Conversely, TREM1 inhibition alleviates ER stress and rescues the autophagy pathway, which ameliorates gut dysbiosis and reduces colitis severity." (PMID 31546668, 2019). "In detail, in a mouse model of dextran sodium sulfate-induced colitis, TREM-1 up-regulation within intestinal macrophages increases the secretion of pro-inflammatory mediators." (PMID 31546668, 2019). "The reducing infiltrating macrophages and neutrophils, which was unexpected due to our initial observation of exacerbated colitis in TREM-1 KO colons." (PMID 31189465, 2019). "While being highly expressed on infiltrating Ly6C+ monocytes and their Ly6C+ MHCII+ descendants in colitis, TREM-1 remains low on mature Ly6C- MHCII+ macrophages even during inflammation 43,44." (PMID 29093489, 2017). "The reduced expression of pro-inflammatory mediators in the entire colonic LP in Trem1−/− x Rag2−/− mice at the late stage of colitis induction certainly also mirrors the decreased cellular infiltration." (PMID 24453980, 2014). "Studies in mice with colitis complemented these findings by showing that gut levels of TREM-1 mRNA directly correlated with disease activity, with increased sTREM-1 levels further measured in mice with more controllable disease." (PMID 25347935, 2014). "In CD4+ T cell- and dextran sodium sulfate-induced models of colitis, Trem1−/− mice displayed significantly attenuated disease that was associated with reduced inflammatory infiltrates and diminished expression of pro-inflammatory cytokines." (PMID 24453980, 2014). "In contrast, Gr1+ cells, representing infiltrating Ly6Chi Gr1int monocytes and Ly6Cint Gr1hi neutrophils, were readily detected in Trem1+/+ x Rag2+/+ mice and Trem1−/− x Rag2−/− mice at 12–13 days post colitis induction." (PMID 24453980, 2014). "In Trem1−/− mice, shortening of the colon was markedly attenuated and total histopathological colitis scores were significantly decreased." (PMID 24453980, 2014). "In a mouse model of DSS-induced colitis, pharmacological or genetic inhibition of TREM-1 has been shown to enhance macroautophagy and chaperone-mediated autophagy via mTOR dysregulation, thereby reducing endoplasmic reticulum stress and suppressing colitis." (PMID 38790914, 2024). "Furthermore, it has been indicated that blocking the TREM1 pathway in mice, for example, significantly reduced colitis inflammation and severity." (PMID 36983834, 2023). "Trem1 expression is upregulated in mice with DSS-induced colitis." (PMID 34795650, 2021). "However, during experimentally induced colitis, the level of Trem1 expression on inflammatory mononuclear phagocytes in mice is increased." (PMID 32987848, 2020). "We therefore speculated that TREM-1 might also regulate macrophage plasticity in the cLP during DSS-induced colitis." (PMID 31189465, 2019). "Moreover, our data demonstrate that intestinal tissue damage from DSS-induced colitis can be alleviated by supplying exogenous IL-22 or WT macrophages to TREM-1 KO mice." (PMID 31189465, 2019). "In detail, in experimental sodium dextran sulfate-induced colitis, TREM-1 inhibition ameliorates dysbiosis and reduces the severity of colitis at clinical, endoscopic, and histological levels, which goes along with alleviation of ER stress and rescuing of the autophagy pathway." (PMID 31546668, 2019). "Again, in a mice model of 2,4,6-trinitrobenzene sulfonic acid-induced colitis, guggulsterone suppresses intestinal inflammation and disease activity via TREM-1 down-regulation, which leads to polarization of macrophages towards M2 phenotype, and reduction of NF-κB and AP-1." (PMID 31546668, 2019).